GZMB (granzyme B)
Diseases named in the same sentence as GZMB in open-access papers (continued):
Sharing a sentence is not in itself a finding about the gene and the disease.
lung carcinoma (continued). "In lung cancer patients, IL-2 treatment reverses CD8+ T cells exhaustion and markedly increases Granzyme B and IFN-γ in malignant pleural effusion." (PMID 30619765, 2018). "This is consistent with a study that has shown the number of granzyme B positive cells is reduced in TIL of breast and lung cancer patients." (PMID 25605488, 2015). "Although we found that both perforin and granzyme B were significantly less expressed at mRNA level in patients with lung cancer, PRF1, but not GRZMB, positively correlated with SPI1 mRNA expression in both cohorts." (PMID 40895524, 2025). "To further verify the significance of Rab37-mediated PD-1 PM presentation in PBMCs from nine lung cancer patients, we cultured human PBMCs for 7 days and then analyzed Rab37 mRNA expression, PD-1+/TIM3+/CD8+ expression, GzmB+/IFN-γ+/CD8+ expression and cancer cell viability of the PBMCs." (PMID 38321486, 2024). "The activation markers GZMB, PRF-1, and IFNγ, migration marker CD183 (CXCR3), and inhibitory marker CD274 (PD-1), were measured and compared in CD8+ T cells with A549 co-cultured, chemokines treated, and patients with late-stage lung cancer." (PMID 34680466, 2021). "Whereas DNT-mediated cytotoxicity to leukemic cells was largely dependent on IFNγ and perforin/granzyme B, this was not the case for lung cancer as blocking these using similar protocols only modestly affected DNT-mediated cytolysis." (PMID 30670085, 2019). "Moreover, TREM2 inhibited NK cell-mediated secretion of anti-tumor molecules, including granzyme B and perforin, which was consistent with the previous findings that TREM2+ mononuclear macrophages suppressed NK cell accumulation and cytolytic activity in lung cancer." (PMID 39135069, 2024). "The results showed that PBMCs from lung cancer patients exhibited significant positive correlation between Rab37 expression and population of PD-1+/TIM3+/CD8+ T cells, which accordingly had negative correlation with anti-tumor activity (GzmB+/IFN-γ+) in CD8+ T cells." (PMID 38321486, 2024). "Given the importance of DNT recognition of lung cancer through NKG2D and DNAM-1 and as TRAIL blocking alone did not completely reduce DNT cytotoxicity in co-cultures, additional mechanisms not inhibited by Fas-FasL pathways such as perforin/granzyme B are likely involved." (PMID 30670085, 2019).
autoimmune disease (35 papers, 2011 to 2025). A disorder resulting from loss of function or tissue destruction of an organ or multiple organs, arising from humoral or cellular immune responses of the individual to their own tissue constituents. "GZMB is associated with human autoimmune diseases and essential effector molecules for natural killer (NK)-cell cytotoxicity." (PMID 35646088, 2022). "These structures sequester CNS tissues from peripheral immune system and Th17 cells that produce Granzyme B are implicated in early events that initiate CNS autoimmune diseases by promoting the disruption of the BBB or BRB." (PMID 34603297, 2021). "To date, the importance of GzmB has been implicated in autoimmune disease, infection immunity, tumor immunity, GVHD and GVT effect." (PMID 27774524, 2016). "More specifically, polymorphism in the GZMB gene, which encodes the enzyme Granzyme B and is involved in cytotoxic T cell-induced apoptosis, may be associated with autoimmune disease, including vitiligo." (PMID 39861486, 2025). "The significant reduction of GZMB+ Breg cells observed in autoimmune diseases such as SLE, contrasted with their increase in transplant patients with renal graft tolerance, underscores the pivotal role these cells play in maintaining immune homeostasis." (PMID 40904455, 2025). "A number of studies have challenged conventional notions, revealing GzmB activity beyond apoptosis, impacting autoimmune diseases, inflammatory disorders, cancer, and neurotoxicity." (PMID 38846935, 2024). "Granzyme B (GzmB)-producing CD4+ T cells have been recently reported to participate in the pathogenesis of autoimmune diseases." (PMID 38841892, 2024). "Here, we show that the MTX-101-mediated inhibition of inhibitory KIR on CD8 Treg enhances their activation, Granzyme B content, and ability to eliminate activated pathogenic CD4 T cells derived from individuals with autoimmune disorders." (PMID 39559361, 2024). "In comparison, GzmB+CD4+ T cells, also known as CD4 CTLs, were mainly associated with viremic states and autoimmune diseases." (PMID 38968186, 2024). "Recently, a new subtype of granzyme B (GrB)-producing Breg cells has been identified, which was proven to be involved in autoimmune disease." (PMID 37500293, 2023). "Blocking/inhibition of Granzyme B production is currently investigated in different therapies, including autoimmune diseases." (PMID 35757700, 2022). "Resistance to Treg-mediated suppression has been reported for effector TH cells in autoimmune disease like multiple sclerosis and type 1 diabetes, and was reported to involve granzyme B and IL-6." (PMID 34073458, 2021). "Growing evidence suggest that antigenic, GzmB-generated peptide fragments are part of a feed-forward loop that sustains the propagation of several autoimmune diseases (reviewed in56)." (PMID 29946113, 2018). "In multiple studies of autoimmune diseases, such as multiple sclerosis, CTLs were found to express increased levels of perforin and granzyme B." (PMID 29636835, 2018). "We further demonstrated that patients in group G2 had a concomitant enrichment in paired kidney samples of granzyme B+ and granzyme K+ T cell subsets, a major driver of tissue inflammation in autoimmune diseases that correlates with an extrafollicular B cell response in LN kidneys." (PMID 40536813, 2025). "Therefore, the significance and versatility of GzmB call for researchers to delve deeper into the complexities of its involvement in inflammatory disorders, autoimmune diseases, and cancer." (PMID 38846935, 2024). "In inflammatory disorders such as atherosclerosis, mast cell-derived GzmB may contribute to arterial damage; in autoimmune diseases such as Rheumatoid Arthritis (RA), Perforin-independent extracellular GzmB activity may also contribute to tissue destruction." (PMID 38846935, 2024).
autoimmune disease (continued). "Patients on B cell depleting therapies for autoimmune diseases have been shown to have an altered immune response to vaccination, for example a lowered percentage of granzyme B+ CD8+ T cells in response to stimulation with the vaccine as compared to healthy controls." (PMID 39086478, 2024). "Our analysis indicated that both subsets showed enhanced cytotoxicity, with sustained increases in expression and chromatin accessibility of key cytotoxic genes such as GZMB, FGFBP2, CTSW, PRF1, which are crucial in other autoimmune disorders." (PMID 39365735, 2024). "Because the perforin/granzyme B pathway has been implicated in potential mechanisms of oligodendrocyte and/or axonal injury and demyelination in MS, our findings together suggest that increased HGF may reduce CTL effector function in CTL-mediated human autoimmune disorders of the CNS." (PMID 32075650, 2020). "In addition to GzmB-expressing CD8+T cells, the role of Gzmb-producing B cells has also been widely noticed in autoimmune diseases." (PMID 36439094, 2022). "The pathological role of extracellular GzmB in autoimmune diseases might not be limited to the physical disruption of important substrates." (PMID 29946113, 2018).
leukemia (35 papers, 2008 to 2025). A malignant (clonal) hematologic disorder, involving hematopoietic stem cells and characterized by the presence of primitive or atypical myeloid or lymphoid cells in the bone marrow and the blood. "For example, there is a robust negative correlation between constitutive Sb9 expression levels and the activity of GzmB in leukemia cells, indicating Sb9 can inhibit the cell apoptosis induced by GzmB." (PMID 38966643, 2024). "This resulted in increased amounts of granzyme B protein, which in their experiments also conferred an enhanced cytolytic activity toward leukemia cell lines." (PMID 32983105, 2020). "Human monocytes primed with LF-IC, but not hLF or M860 alone, or control ICs, showed strong tumoricidal activity on leukemia cell lines Jurkat and Raji through induction of secreted Granzyme B (GzB)." (PMID 31600968, 2019). "iNKT cells are capable of inducing apoptosis of leukemia cells through the release of perforin and granzyme B or through Fas signaling." (PMID 30127790, 2018). "Previous study has shown that DMF metabolite MMF can augment the NK cell lysis of K562 and RAJI leukemia cells through CD107a and Granzyme B." (PMID 29209333, 2017). "For example, in Jurkat leukemia cells, disruption of Bim/Mcl-1 binding has been postulated to contribute to granzyme B-mediated apoptosis." (PMID 24594907, 2014). "Additionally, GZMB expression progressively increases in ST2+ Treg cells from day 5 to day 20 with leukemia development in two leukemia models." (PMID 40691440, 2025). "Here, we showed that ST2+ Treg cells that are non-engineered and non-professional cytotoxic T cells are equipped with high levels of GZMB (up to 40%) and can directly kill leukemia-primed effector T cells at a low ratio of 1:1 to promote tumor progression, adding a second mechanism of suppression." (PMID 40691440, 2025). "In addition, the higher expression of Granzyme B in CIML NK cells has previously been reported by other authors who have described increased lysis of leukemia target cells in vitro." (PMID 37908353, 2023). "Data on anti-leukaemia activity were also corroborated by the quantification of inflammatory cytokines, namely granzyme B (Granz B), interferon gamma (IFN-γ) and tumour necrosis factor alpha (TNF-α), both in vitro and in the plasma of mice treated with CAR.CD123-NK cells." (PMID 36335396, 2022). "The two diterpenes increased granzyme B expression in NK cells, likely through the phosphorylation of ATF-2, c-Jun, and CREB, transcription factors involved in the regulation of granzyme B. The net result was the enhancement of the cytolytic activity of NK cells in leukaemia cell lines." (PMID 36364160, 2022). "Finally, CTVlo TCRTg101 from livers of leukemia-bearing animals were also unable to effectively kill C1498 cells directly ex vivo, despite their inducible expression of GzmB." (PMID 34758311, 2021). "Finally, donor-type CD44+CD8+ effector T cells purified from the GC-treated BM cells expressed granzyme B and mediated equivalent killing on a per-cell basis to the vehicle-treated T cells in redirected cytolysis assays against leukemia cells." (PMID 34637399, 2021). "Our findings demonstrate that CD8+ T cells from Cat-Tg mice have enhanced activation markers, significantly altered CD8+ T cells phenotype, enhanced expression of Granzyme B and Perforin, and exert better cytotoxicity against primary leukemia cells than CD8+ T cells from WT mice." (PMID 34359702, 2021). "In addition to functional cytotoxicity assays, we measured the release of Perforin and Granzyme B by NK cells co-cultured with a leukemia target cell line (HL60)." (PMID 29342200, 2018). "CD19-CAR-NK cells generated using CD19-CAR mRNA-LNPs killed Daudi and Nalm-6 leukemia cell lines in a dose-dependent manner and secreted IFN-gamma and Granzyme B at significantly higher levels than NK cells." (PMID 37686170, 2023).
leukemia (continued). "In the bone marrow, they had interstitial and intrasinusoidal linear infiltration of T cells expressing CD3, CD8, CD57, and granzyme B described by Morice and colleagues as a typical pattern for T-LGL leukemia." (PMID 18474096, 2008). "In fact, a high-avidity TCR, S117A-TCR-transduced CD4+ T cells had a higher frequency of granzyme B/perforin-double positive cells and showed more potent cytotoxicity against WT1-expressing and HLA-DPB1*05:01-positive leukemia cells, compared to wt-TCR-transduced CD4+ T cells." (PMID 36939853, 2023). "The ability of T cell subsets that do not express granzyme B protein to respond to TGF-β by increasing VISTA expression may be the crucial biochemical mechanism used by granzyme B-negative T cell lymphoma/leukemia cells." (PMID 35223897, 2022). "As for GZMB+ Bregs, we found that BANK1 was decreased in other subtypes of Bregs, including IL10+ and CD24hiCD38hi transitional regulatory B cells, along with BANK1 was down-regulated in activated/differentiated B cells, as in CD40-activated B cells, in leukemia and plasma cells." (PMID 33815360, 2021). "Interestingly, the Tregs A subpopulation is positive for already reported markers of CLL-related Tregs, including IL-10, LAG-3, granzyme B, EOMES, as well as share a unique gene expression signature of chemokines that may support leukemia progression and formation of leukemic microenvironment." (PMID 35296093, 2022). "It remains to be determined whether increased granzyme B in CD8+ T cells may be responsible for killing of autologous lymphocyte CD4+ T cells and/or B cells, therefore, contributing further to CD4 and B cell lymphopenia, which is feature of Good syndrome without leukemia." (PMID 26429871, 2015).
pancreatic cancer (35 papers, 2013 to 2025). "Coincidentally, granzyme B, as another typical granzyme, was also found to be expressed in human urothelial carcinoma samples and pancreatic cancer and to be associated with the tumor epithelial-mesenchymal transition and invasion in vitro." (PMID 25788270, 2015). "Furthermore, a study on pancreatic cancer reported that a close proximity of immunosuppressive IL10+ myelomonocytes to cytotoxic granzyme-B+ CD8+ T-cells instead of PD-1+ CD4 + T-cells was associated with shorter survival in non-neoadjuvant treated patients." (PMID 38386105, 2024). "The reduction in perforin and granzyme B directly compromises NK cell function, promoting pancreatic cancer progression." (PMID 41007358, 2025). "validated GZMB expression in pancreatic cancer cell lines, discovering that the human pancreatic cancer PT45 cell line expresses it." (PMID 41567188, 2025). "In the same assay, release of granzyme B in response to pancreatic cancer MIA PaCa-2, which is a weaker target of MC.7.G5, was fully reliant on TCR replacement." (PMID 39744940, 2025). "Subsequent research by D’Eliseo D and others revealed that both bladder and pancreatic cancer cells express GZMB, which enhances tumor invasiveness." (PMID 41567188, 2025). "A study using a murine pancreatic cancer model revealed that lactate treatment decreased the production of perforin and granzyme B by NK cells." (PMID 41007358, 2025). "Nevertheless, a recent study reported that pancreatic cancer-derived EVs carrying Hsp70 can activate NK cells and induce tumor apoptosis through released granzyme B (GrB) and perforin." (PMID 39040921, 2024). "Dihydroartemisinin, one of ART derivatives, strengthens γδT cell killing activities against pancreatic cancer cells through increasing intracellular perforin, granzyme B, and IFN-γ production signaling pathways." (PMID 35785030, 2022). "The expression of GZMB by cancer cells has only been reported in bladder and pancreatic cancers where extracellular GZMB was found to promote their invasion in vivo." (PMID 32764784, 2020). "Together, our results support that Cxcr3, potentially by interacting with Cxcl9/Cxc10 + cDC1s in the spleen, promotes GzmB + cytotoxic T cells that may mitigate pancreatic cancer metastasis." (PMID 36472588, 2023). "However, after the deletion of GPR116 receptor, the proportion of NK cells in pancreatic cancer increased significantly, and the expression level of GzmB and IFNγ in NK cells were also increased." (PMID 36895027, 2023). "Furthermore, in pancreatic tumors treated with both a lysyl oxidase inhibitor and immune therapy, a decrease in pro-tumorigenic TAMs and an increase in CD8+ Granzyme B+ T-cells (anti-tumorigenic) was associated with increased survival." (PMID 35205728, 2022). "In addition, both CD8 +T cells and activated Granzyme B+T cells were significantly increased in the combination group, which was consistent with the results in the pancreatic cancer in vivo model." (PMID 35288467, 2022). "Interestingly, the researchers discovered that the n-3 polyunsaturated fatty acid docosahexaenoic acid (22:6n-3; DHA), an active derivative of fish oil, dose-dependently downregulated GZMB in human pancreatic cancer PT45 cells and human bladder cancer RT112 cells." (PMID 41567188, 2025). "Remarkably, a similar trend was observed in a mouse model of orthotopic pancreatic cancer, where Sin3B loss significantly augmented CD8+ T cell infiltration, alongside heightened cytotoxicity against tumor cells, as evidenced by the upregulation of IFNγ and GzmB." (PMID 39316363, 2024). "Similar to what we observed with the anti-Gas6 treatment, warfarin reduced pancreatic cancer metastasis to the lungs and increased the number and activation of NK cells in lungs and mesenteric lymph nodes, as shown by the increase in NKp46+ and granzyme B expression." (PMID 32174917, 2020).